MPP2 (MAGUK p55 scaffold protein 2)
Description:
Postsynaptic MAGUK scaffold protein that links CADM1 cell adhesion molecules to core components of the postsynaptic density (By similarity). In CA1 pyramidal neurons, required for synaptic KCNN2-containing channel function and long-term potentiation expression (By similarity). Seems to negatively regulate SRC function in epithelial cells.
Synonyms: DLG2; DKFZp761D0712
Tractability: Antibody: its Gene Ontology location is reachable by antibodies, with medium confidence. PROTAC: ubiquitination databases record sites on it; its protein half-life has been measured.
Gene: Protein-coding gene on chromosome 17 (43,875,357 to 43,909,711, reverse strand). Ensembl gene ENSG00000108852.
Subcellular location: Cytoplasm, cytoskeleton; Membrane; Cell projection, dendrite; Postsynaptic density
Gene Ontology:
Molecular function: protein binding
Biological process: excitatory postsynaptic potential; long-term synaptic potentiation; protein homooligomerization
Cellular component: cytoskeleton; membrane; cell-cell junction; dendrite membrane; dendritic shaft; dendritic spine; plasma membrane; postsynaptic density; dendrite; organelle
Genetic constraint (gnomAD): Loss-of-function variants: 41 observed, 60.36 expected, observed/expected ratio (o/e) 0.68, 90% interval 0.53 to 0.88. The upper end of that interval is the gene's LOEUF score, 0.88, which puts it in group 3 of 6, group 1 being the genes least tolerant of losing a copy. Missense variants: 632 observed, 774.94 expected, observed/expected ratio (o/e) 0.82, 90% interval 0.76 to 0.87. Synonymous variants: 300 observed, 316.39 expected, observed/expected ratio (o/e) 0.95, 90% interval 0.86 to 1.04.
Homologues: Orthologues: chimpanzee MPP2 (99% identical), macaque MPP2 (99% identical), pig MPP2 (98% identical), rat Mpp2 (97% identical), dog MPP2 (97% identical), mouse Mpp2 (96% identical), rabbit MPP2 (96% identical), guinea pig MPP2 (93% identical), tropical clawed frog mpp2 (75% identical), zebrafish mpp2b (72% identical), zebrafish mpp2a (69% identical), Drosophila melanogaster vari (42% identical), and 3 more. Paralogues in human: PALS2 (68% identical), CASK (42% identical), MPP7 (38% identical), MPP3 (34% identical), MPP1 (34% identical), PALS1 (32% identical), MPP4 (32% identical).
Diseases named in the same sentence as MPP2 in open-access papers:
MPP2 is named in the same sentence as 22 diseases in open-access papers, as found by Europe PMC text mining. Sharing a sentence is not in itself a finding about the gene and the disease. The quoted sentences say what the papers report.
colon cancer (3 papers, 2022 to 2025). "Additionally, RT-PCR confirmed the association of CUL7, ENO2, and MPP2 expression levels with colon cancer." (PMID 40260289, 2025). "CUL7, ENO2, and MPP2 were identified as potential antigens for colon cancer mRNA vaccines, with MPP2 showing particular immunological relevance." (PMID 40260289, 2025). "The overexpression level of MPP2 in liver cancer cells promotes their apoptosis, and Huang C. reported that MPP2 is related to the 5-year survival rate of colon cancer patients." (PMID 36117173, 2022). "Thus, This study identifies CUL7, ENO2, and MPP2 as potential antigens for colon cancer mRNA vaccines." (PMID 40260289, 2025). "Therefore, the relationship between MPP2 and colon cancer and its specific mechanism remains to be explored." (PMID 36105107, 2022).
liver cancer (3 papers, 2022 to 2025). An epithelial or non-epithelial malignant neoplasm that arises from the liver. "Prior research has shown that the MPP2 gene, a member of the MPP family, exhibits low expression in liver cancer tissues compared to high expression in normal liver tissues." (PMID 40260289, 2025).
leukemia (2 papers, 2020 to 2022). A malignant (clonal) hematologic disorder, involving hematopoietic stem cells and characterized by the presence of primitive or atypical myeloid or lymphoid cells in the bone marrow and the blood. "The observed increase of the MPP2 population and corresponding drop in myeloid progenitors suggests that leukemia development impairs MPP2 to myeloid progenitor differentiation." (PMID 33154494, 2020). "This contrasts with adult bone marrow, where transformation of HSCs results in CD41+ leukemia, while transformation of MPP2, MPP3, and MMP4 cells results in both CD41+ and Gr1+ leukemias, with Gr1+ cells being more predominate in the transformed MPP3 and MPP4 populations." (PMID 36136600, 2022).
Alzheimer disease (1 paper, 2020). A progressive, neurodegenerative disease characterized by loss of function and death of nerve cells in several areas of the brain leading to loss of cognitive function such as memory and language. "Potentially, pathological pathways included Apoptosis signaling pathway (P00006, FASL), FAS signaling pathway (P00020, FASL) and Alzheimer disease-presenilin pathway (P00004, MPP-2)." (PMID 32804078, 2020).
Anxiety (1 paper, 2020). Intense feelings of nervousness, tension, or panic often arise in response to interpersonal stresses. "In contrast to the naïve mice, ethological findings in MS mice revealed lowered visceral pain threshold, more evident anxiety- and depression-like behaviors, and downregulated expression of membrane SK2 protein and MPP2 protein." (PMID 33029124, 2020).
bipolar disorder (1 paper, 2022). A disorder of the brain that causes unusual shifts in mood, energy, activity levels and the ability to carry out day-to-day tasks. "In the Bipolar disorder dataset, four risk variants were found to overlap with hmsLRI-E which were connected to the NR2C2AP gene (two variants), the MPP2 gene (one variant), and the LMS12 gene (two variants)." (PMID 35887306, 2022).
cystic teratomas of the ovary (1 paper, 2022). "Among the prevalent mutated genes, 7 with the same variant in exons with changes in protein coding are important for the development of mature cystic teratomas of the ovary: PTGFRN, DUSP5, MPP2, PHLDA1, PRR21, GOLGA6L2, and KRTAP4-2." (PMID 36289533, 2022).
uveitis (1 paper, 2023). An inflammatory process affecting a part of or the entire uvea. "Further studies are needed to elucidate the roles of overexpression of the MPP2-K315N mutant in MPP2-K315N KO mice in the development of uveitis in the future." (PMID 37828081, 2023). "In conclusion, we identified a de novo mutation, MPP2 p.K315N (c.G945T, NM_001278372), in VKH disease using WES and then demonstrated the deleterious role of the MPP2-K315N mutation in the occurrence and development of uveitis." (PMID 37828081, 2023). "Collectively, our data showed for the first time that the MPP2-K315N mutation may increase genetic susceptibility to VKH disease and provides a novel target for uveitis therapy." (PMID 37828081, 2023). "During in vitro experiments, we performed a series of functional assays in MPP2 mutant ARPE19 cells without any stimulation, which clarified the effect of MPP2 mutation on the occurrence of uveitis." (PMID 37828081, 2023). "However, the role of MPP2 mutations in pathological conditions has not been investigated, and further experiments will be carried out on inflammation-stimulated ARPE19 cells with MPP2 mutations to fully elucidate the critical role of MPP2 mutations in the development of uveitis." (PMID 37828081, 2023).
tumor (10 papers, 2017 to 2025). "Recent studies have further linked MPP2 expression to immune activation in tumors, demonstrating its prognostic potential and association with tumor-infiltrating lymphocytes (TILs)." (PMID 40260289, 2025). "miR-34a exhibits a dual effect in bladder cancer by upregulating the expression of PTEN, a tumor suppressor gene, while downregulating MPP2, a gene associated with tumor progression." (PMID 37835417, 2023). "The MPP2 gene represents a promising target antigen for COAD mRNA tumor vaccine research, particularly for patients most likely to benefit." (PMID 40260289, 2025). "An additional phase I (NCT04214392) study is recruiting MPP2+ rGBM patients to undergo CART therapy with a chlorotoxin tumor-targeting domain." (PMID 37568717, 2023). "MTA1 mediated the tumor cell migration and invasion in cultured cells through the regulation of E-cadherin, MPP2, and MPP9 via the NF-κB pathway." (PMID 33059651, 2020). "The results identified a correlation between three tumor antigens—CUL7, ENO2, and MPP2—and both prognosis and APC infiltration in patients with COAD." (PMID 40260289, 2025). "IHC analysis of xenografted tumour tissues revealed that MPZ, SCARA3, MPP2 and PBXIP1 expression levels were low in the SW620/sh-MPZ, SW620/sh-SCARA3, SW620/sh-MPP2 and SW620/sh-PBXIP1 groups." (PMID 36117173, 2022).
cancer (5 papers, 2012 to 2025). A tumor composed of atypical neoplastic, often pleomorphic cells that invade other tissues. "Foxm1 transcription factor (also known as HFH-11B, Trident, Win or MPP2) plays an important role in the pathogenesis of various cancers and is a critical mediator of post-injury repair in multiple organs." (PMID 23144938, 2012). "At present, the role and mechanism of MPP2 in cancer are rarely reported." (PMID 36105107, 2022). "MPP2 expression was significantly higher in cancer tissues compared to normal tissues (P < 0.01), while CUL7 expression was significantly lower in cancer tissues (P < 0.01)." (PMID 40260289, 2025). "CCND1 (Cyclin D1), MPP2 (Membrane palmitoylated protein 2), Bax, Bcl2, HIF1A and VEGFA are transcriptionally regulated molecules that are related to cell proliferation, apoptosis and cancer cell invasion and metastasis processes." (PMID 39834948, 2024). "For unreported model genes (MPZ, SCARA3, MPP2 and PBXIP1), recent studies have demonstrated that those genes are involved in the development of cancers." (PMID 36117173, 2022).
infection (3 papers, 2014 to 2021). The state of being infected such as from the introduction of a foreign agent such as serum, vaccine, antigenic substance or organism. "LKS+ cells (containing LT-HSC, MPP2, MPP3 and MPP4 subpopulations) significantly rose in the spleen of the 7-day PCA2-infected mice, and dropped at 14-day post PCA2 infection." (PMID 34975887, 2021). "Infection alone produced an accumulation of MPP1, MPP2, MPP3, and MPP4 cells, and, as with HSCs, MPP1 and MPP2 cells accumulated to a lesser extent with infection plus imatinib compared to infection alone." (PMID 25822986, 2015).
MPP2 also shares sentences with these, for which no sentence is quoted: glioblastoma (4 papers); asthma (1); astrocytoma (1); breast carcinoma (1); colorectal tumour (1); depression (1); fibrosis (1); gastric cancer (1); malignant brain tumor (1); melanoma (1); Wilms tumor (1).